DNMT3B (DNA methyltransferase 3 beta)
Diseases named in the same sentence as DNMT3B in open-access papers (continued):
Sharing a sentence is not in itself a finding about the gene and the disease.
prostate carcinoma (continued). "Finally, the pattern of genome-wide hypermethylation and DNMT3b over-expression combined with tissue cadmium levels may provide biomarkers to specifically identify cadmium-induced human prostate cancers." (PMID 17938735, 2007). "In prostate cancer, the upregulation of REX1 has been shown to recruit DNMT3B to the RASSF1A promoter, leading to its transcriptional silencing via a de novo methylation-dependent mechanism." (PMID 41008642, 2025). "We analyzed the expression of DNMT1, DNMT3A, DNMT3B, and the class I HDACs HDAC1, HDAC2, HDAC3, and HDAC8 in the PRAD and Taylor data sets and their correlation to HLA-I expression in prostate cancer." (PMID 36050516, 2022). "Earlier studies in prostate cancer have analyzed various methyltransferases and found that DNMT1 expression was found to be lower than DNMT3b." (PMID 28235398, 2017). "For example, in LnCaP prostate cancer cells (androgen–dependent) SFN significantly decreases expression of DNMT1 and DNMT3b on mRNA and protein level but the plant HDI has slight effect on DNMT1 protein level in PC3 and BPH-1 prostate cancer cells." (PMID 26703571, 2015). "We assessed the effects of SFN and DIM on the expression of DNMT1, DNMT3A, and DNMT3B in normal prostate epithelial cells (PrEC), androgen-dependent (LnCAP) and androgen-independent (PC3) prostate cancer cells." (PMID 24466240, 2014). "Taken together, we show that mahanine treatment induces the proteasomal degradation of DNMT1 and DNMT3B via the inactivation of Akt, which facilitates the demethylation of the RASSF1A promoter and restores its expression in prostate cancer cells." (PMID 24001151, 2013). "The degradation of DNMT1 and DNMT3B prompts the demethylation of the promoter of the silenced tumour suppressor gene RASSF1A, leading to the restoration of its expression in prostate cancer cells." (PMID 24001151, 2013). "Specifically, ATRA inhibits the proliferation of DU145 prostate cancer cells through reducing the methylation level of HOXB13 promoter induced by EZH2 and DNMT3b." (PMID 22808286, 2012). "We assessed the effects of SFN on the expressions of DNMTs (DNMT1, DNMT3a, and DNMT3b) in benign hyperplasia (BPH-1), LnCap and PC3 prostate cancer cells." (PMID 22303414, 2011). "In prostate cancer cells, PC3 cells, DNMT3B expression was shown to be induced by X-ray radiation." (PMID 41369374, 2025). "Harmine does not affect the mRNA expression of DNMT3A and DNMT3B but rather directly inhibits their activity to suppress prostate cancer cell proliferation." (PMID 38590646, 2024). "Furthermore, Western blot analysis demonstrated that saffron treatment induced changes in the expression of other key genes (DNMT1, DNMT3b, MBD2, CD44, HDAC3, c-Myc, NF-kB, TNFα, AR, N-RAS, and PTEN) in prostate cancer cells." (PMID 38201944, 2023). "In the complementary studies, we utilized small interfering RNA (siRNA) to selectively target pivotal DNA methyltransferases (DNMTs), including NDMT1, DNMT3A, and DNMT3B, with the primary objective of elucidating their roles in the modulation of SPDEF protein expression within prostate cancer cells." (PMID 37900138, 2023). "Indeed, antiandrogen medication given to patient with prostate cancer increased DNMT3A and DNMT3B expression." (PMID 35360841, 2022). "Our data clearly indicates that mahanine treatment causes a decline in the levels of DNMT1 and DNMT3B, without affecting the levels of DNMT3A, in both LNCaP and PC3 prostate cancer cells." (PMID 24001151, 2013). "In this study we have silenced the expression of DNMT3b in prostate cancer derived PC3 cells, which have not been studied previously, and determined its consequences on gene specific methylation and expression as well as on cellular processes such as apoptosis and cell migration." (PMID 18798999, 2008).
prostate carcinoma (continued). "Furthermore, the DNMT3B rs2424913 SNP may contribute to reduced methylation of CpG islands of the MYOD and MLH1 genes in normal colonic mucosa of patients with CRC, and with increased promoter methylation of TSGs related to the development of prostate cancer." (PMID 23666104, 2013). "We show that mahanine induces the degradation of DNMT1 and DNMT3B via the ubiquitin-proteasome mediated pathway in both androgen-responsive LNCaP and androgen receptor-negative PC3 human prostate cancer cells." (PMID 24001151, 2013). "Noticeably, treatment of AR− prostate cancer cells with ATRA did not change the expressions of HOXB13, EZH2 and DNMT3b at mRNA level, implicating a different mechanism of ATRA action in this particular cell background." (PMID 22808286, 2012).
leukemia (30 papers, 2010 to 2025). A malignant (clonal) hematologic disorder, involving hematopoietic stem cells and characterized by the presence of primitive or atypical myeloid or lymphoid cells in the bone marrow and the blood. "Although DNMT3B was rarely mutated in AML, studies have proved that loss of DNMT3B accelerated MLL-AF9 leukemia progression and increased expression of DNMT3B in LSC delayed leukemogenesis." (PMID 32597790, 2020). "Dnmt3b was reported to encode a DNA methyltransferase, which is involved in aberrant epigenetic changes that lead to leukemia." (PMID 31168296, 2019). "It is worth noting that NCL expression also positively associates with the levels of DNMT3A and DNMT3B in leukemia patients." (PMID 25015109, 2014). "However, ectopic DNMT3B expression was reported to delay leukemogenesis, and the loss of DNMT3B accelerated MLL-AF9 leukemia progression." (PMID 32597790, 2020). "Previous mechanistic studies of AZA resistance in human leukemia cell lines found that the mRNA levels of the genes encoding DNMT1, DNMT3a, and DNMT3b were increased in HMA-resistant cells." (PMID 38731939, 2024). "Nevertheless, DNMT3B seems to play a opposite role in the oncogenesis of leukemia: high expression of DNMT3B contributes to impaired leukemogenesis, and the absence of DNMTB accelerates the progression of MLL-AF9." (PMID 37686409, 2023). "In leukemias, the absence or decrease of DNMT3B is an event that favors the malign transformation and has target genes such as C-met78." (PMID 36460706, 2022). "Abnormal expression of DNMT3B isoforms is frequently observed in several types of cancer, such as breast, lung, kidney, gastric, liver, skin, leukemia, and sarcoma." (PMID 36361550, 2022). "DNMT3B is expressed as an oncogene in various of tumors, including leukemia, liver cancer, and bladder cancers." (PMID 34631874, 2021). "Another group built a six-gene leukemia stem cell (LSC) score with the incorporation of DNMT3B, GPR56, CD34, SOCS2, SPINK2, and KIAA0125 expressions for pediatric AML." (PMID 33225420, 2021). "CCND2, DNMT3B, SOX4, and IKZF2, all previously reported to associate with leukemia development, were found within the positively correlated genes." (PMID 33597968, 2020). "It has also previously revealed that Dnmt3b-mediated DNA methylation was crucial in the progression of leukemia." (PMID 31168296, 2019). "A recent study found that Dnmt3b-mediated DNA methylation acted an essential role in the development of leukemia." (PMID 31168296, 2019). "Emerging data indicate that the DNMTs, including DNMT1, DNMT3a, and DNMT3b, which catalyze promoter methylation, are upregulated in leukemia." (PMID 26673819, 2016). "By analyzing the GEO datasets, we found that NCL levels are in parallel with the expression of DNMT1, DNMT3A and DNMT3B in leukemia patients." (PMID 25015109, 2014). "In another study, HOXB3 was found to interact with DNMT3B to promote leukemia development." (PMID 40275933, 2025). "We first analysed the DA1-3b leukemia model and among the 70 commonly mutated genes in dormant leukemia DA1-3b/D365 and parental DA1-3b cells, ten genes (Ttc7b, Dnmt3b, Ap1b1, Ne1, Nedd4, Acy1, Cyp11a1, Htr2c, Magee1 and Gdi1) were amplified in dormant and parental cells." (PMID 39223638, 2024). "It has been suggested that increased expression of maintenance DNA methyltransferases (DNMTs) or de novo expression of specific DNMTs (e.g., DNMT3A and DNMT3B) contribute to the development of leukemia by inducing aberrant hypermethylation of important genomic regions." (PMID 38731939, 2024).
leukemia (continued). "CDK6 was also found to be positively associated with genes identified to contribute to the development of leukemia, including CCND2, DNMT3B, SOX4, and IKZF2, as well as being negatively associated with anticancer microRNAs, including miR-187, miR-9, miR-582, miR708, and miR-362." (PMID 33597968, 2020). "Besides DNMT3a and DNMT3b, leukemia-derived microvesicles also increased the protein and mRNA levels of AICDA (activation-induced cytidine deaminase) in recipient cells." (PMID 31752198, 2019). "HOXB3-CDCA3/DNMT3B signaling pathway contributes to leukemogenesis and maintenance of leukemia." (PMID 29439669, 2018). "Thus, restoring the expression of miR-375 has anti-leukemia ability by disrupting the miR-375-HOXB3-CDCA3/DNMT3B regulatory circuitry." (PMID 29439669, 2018). "Moreover, DNMT3B has been shown to play a role in leukemia development and maintenance of Leukemia stem cell function." (PMID 30405408, 2018). "Therefore, HOXB3-CDCA3/DNMT3B signaling pathway might play an important role in the proliferation and colony formation of leukemia stem and progenitor cells." (PMID 29439669, 2018). "HOPX, DOCK1, DNMT3B, MMRN1, and ARHGAP22 genes were reported as important leukemia stem cell markers." (PMID 33225420, 2021). "Indeed, PU.1/DNMT3A/DNMT3B interactions may be favored by high amounts of PU.1 in leukemia." (PMID 29449903, 2018). "When microvesicles were treated with RNase, the level of DNMT3a, DNMT3b, and AICDA decreased, indicating that leukemia-derived microvesicles influence the methylation status of recipient cells via transmission of microvesicular RNA." (PMID 26582468, 2015). "This is in agreement with previous data on CD34+ leukemia cell lines, such as KG1, showing high expression of DNMT3B." (PMID 25948775, 2015).
melanoma (30 papers, 2013 to 2026). A malignant, usually aggressive tumor composed of atypical, neoplastic melanocytes. "Both DNMT3A and DNMT3B manifest oncogenic properties in melanoma and have been linked with unfavorable clinical outcomes." (PMID 38541782, 2024). "In preclinical studies, Dnmt3b deficiency was shown to prevent melanoma development in Braf- and Pten-deficient murine melanocytes through modulation of the mTOR pathway." (PMID 37160317, 2023). "The loss of Dnmt3b in a Braf/Pten mouse model resulted in a dramatic decrease in melanoma formation." (PMID 33024276, 2020). "DNMT3B expression increases with melanoma progression, and DNMT3B has been associated with p16INK4A methylation in melanoma, as well as regulating mTORC2 signaling in a melanoma model in vivo." (PMID 28396701, 2017). "DNMT3B loss dramatically suppresses melanoma formation in the Braf/Pten murine model." (PMID 36077374, 2022). "In melanoma, DNMT3B was found as a negative regulator of miR-196b, and DNMT3B loss reduced miR-196b promoter methylation and increased its expression, which suppressed formation and growth of melanoma." (PMID 35129056, 2022). "DNMT3B expression is upregulated in melanoma and is associated with reduced patient survival." (PMID 31581557, 2019). "In silico geometry optimization and docking were carried out for melanoma-associated targets (MITF and DNMT3B)." (PMID 41590097, 2026). "Their findings indicate that DNMT3B exerts a pro-tumorigenic function in human melanoma, while its depletion significantly inhibits melanoma development in the Braf/Pten mouse melanoma model." (PMID 37705098, 2023). "DNMT3B/miR-196b/Rictor axis holds promise as a viable therapeutic target for the treatment of melanoma." (PMID 37705098, 2023). "These outcomes firmly establish Dnmt3B as a modulator of melanoma formation by influencing miR-196b and subsequently regulating the signaling pathways associated with mTORC2." (PMID 37705098, 2023). "DNMT3B is also often proved to be overexpressed in tumor cells, for instance, it plays a cancer-promoting role in human melanoma." (PMID 36091786, 2022). "Abnormal DNA methylation is considered as an important epigenetic marker in melanoma pathogenesis and dysexpression of methyltransferases such as DNMT3B, can alter methylation pattern in genes promoter." (PMID 34914337, 2021). "On the other hand, the DNMT3B gene was significantly upregulated in melanoma cells compared to control cells (p = 0.0015)." (PMID 34914337, 2021). "Decreased expression of GAS7 gene in melanoma cells can be attributed to increased expression of genes involved in methylation (DNMT3B)." (PMID 34914337, 2021). "In any case, the results clearly indicated that Dnmt3b is a pro-tumorigenic protein in melanoma and necessary for melanoma formation in the context of BRAF mutation and loss of phosphatase and tensin homolog (PTEN)." (PMID 33024276, 2020). "Our previous study showed that miR-29c was negatively correlated with the expression of DNMT3B in melanoma." (PMID 29796115, 2018). "Previous study showed that miR-29c was negatively correlated with the expression of DNMT3B in melanoma in our group." (PMID 29796115, 2018). "The difference in global methylation levels and protein expression of DNMT1 and DNMT3b prompted us to investigate the methylation profiles of the proliferative and invasive phenotype melanoma cells." (PMID 25885555, 2015). "DNMT3b had about 50% less protein expression in the proliferative melanoma cell cultures compared to the invasive melanoma cell cultures." (PMID 25885555, 2015). "DNMT3a and DNMT3b, the de novo DNA methyltransferases, were shown to have increased expression in metastatic melanomas compared to primary melanomas." (PMID 25885555, 2015). "Amongst these, ABCB1, DNMT3B, EPAS1, JARID1B and TERT have previously been designated as melanoma CSC(-associated) markers (and reviewed in 13)." (PMID 24098529, 2013).
melanoma (continued). "In addition, the depletion of DNMT3A in mouse melanoma cells inhibited tumor growth and metastasis in a xenograft model, while DNMT3B increased proportionally with melanoma progression, leading to the silencing of tumor suppressor gene p16INK4A." (PMID 40136320, 2025). "In melanoma, positive associations between expression of PRAME and DNMT3A and DNMT3B were seen." (PMID 38541782, 2024). "Micevic and colleagues explored the precise signaling pathways regulated by DNMT3B in melanoma." (PMID 37705098, 2023). "Moreover, a critical role for Rictor/mTORC2 in melanoma progression has been indicated in the Braf/PTEN mouse melanoma model downstream of the DNA methyltransferase DNMT3B, which is frequently overexpressed in several tumors." (PMID 36077374, 2022). "Protein and mRNA expression of DNMT3B were found enhanced in melanoma and GC." (PMID 34380460, 2021). "Among all DNMTs, DNMT3B plays a major pro-tumorigenic role in human melanoma." (PMID 34914337, 2021). "Since we did not observe changes in the expression of the validated miR-29 targets AKT3, MCL1, and DNMT3B, we identified new targets whose repression may contribute to restricting melanoma development." (PMID 33808771, 2021). "Among the three major DNMTs, DNMT3A and DNMT3B are commonly overexpressed in melanoma." (PMID 33024276, 2020). "Additionally, SNPs in DNMT1 (rs2228612, rs2228611, and rs2114724) and DNMT3B (rs406193 and rs2424932) have been shown to affect the clinical course and disease outcome in patients with melanoma." (PMID 33024276, 2020). "Thus, this study establishes DNMT3B as a regulator of melanoma development via its influence on mTORC2 signaling and suggests a new therapeutic target in melanoma." (PMID 31370278, 2019). "Our data indicate that SIRT1 and DNMT3B co-participate in Mxd1 epigenetic silencing in melanoma." (PMID 29383100, 2017). "Loss of DNMT3B in the mouse model delayed the melanoma formation suggesting that other DNMTs do not adequately compensate for DNMT3B loss and suggesting nonredundant roles for DNMTs in melanoma and DNMT3B, in particular, may play specific, nonredundant roles." (PMID 31828117, 2019). "In melanoma cells, SIRT1 silences MXD dimerization protein 1 (Mxd1) by binding to DNMT3B, thereby increasing resistance to dead-cancer-induced stress, which leads to increased Myc activity and drives melanoma progression." (PMID 39479446, 2024). "Conversely, melanomas revealed frequent expression of methyltransferases DNMT3A (49/66, 74%) and DNMT3B (44/66, 67%)." (PMID 38541782, 2024). "To further interrogate the role of DNMTs in melanoma-STING silencing, we transfected B16-F10 cells with small interfering RNA (siRNA) targeting DNMT1, DNMT3A, and DNMT3B." (PMID 36949064, 2023). "Accordingly, in the present study we aimed to predict regulatory effect of miRNAs on DNMT3B and GAS7 genes expression in melanoma cell line." (PMID 34914337, 2021). "The results demonstrated that the DNMT3B and GAS7 genes were significantly up- and down-regulated in melanoma cells compared to melanocytes, respectively." (PMID 34914337, 2021). "To investigate the possible indirect effect of miRNAs on expression of DNMT3B and GAS7 genes, we quantified the expression of these genes in melanoma cells and normal melanocytes." (PMID 34914337, 2021). "In conclusion, it seems that our predicted miRNAs have a regulatory role on DNMT3B and GAS7 genes and alteration of their expression can be considered as a new therapeutic approach (alone or in combination with other methods) for melanoma." (PMID 34914337, 2021). "As an alternative, in this study, we used bioinformatics prediction to find miRNAs that are involved in the regulation of DNMT3B and GAS7 genes of melanoma cells and melanocytes." (PMID 34914337, 2021). "In drug-tolerant BRAFV600E melanoma cells that emerged following MAPK inhibitor treatment, DNMT3A, DNMT3B, and DNMT1 were differentially expressed, resulting in low global DNA methylation levels." (PMID 31581557, 2019).
melanoma (continued). "PI3K signaling, which is activated in most cancers, can regulate methylation of imprinted regions, and inactivation of PI3K signaling decreases DNMT3B level in HCC, melanoma, and prostate and other cancers." (PMID 28396701, 2017). "In further support, the melanoma SP shows upregulated expression of factors that by others have been assigned to (candidate) melanoma CSC, including ABCB1, DNMT3B, EPAS1, JARID1B and TERT." (PMID 24098529, 2013). "Therefore, in the present study, we aimed to predict microRNAs involved in DNMT3B gene methylation through bioinformatics approaches and examined their effect on DNMT3B and GAS7 genes expression in melanoma cells." (PMID 34914337, 2021). "We have also seen an inverse correlation between this miR-203 and DNMT3b in nonmetastatic melanoma cells compared to normal melanocytes." (PMID 26618174, 2015). "Similarly, the lack of DNMT3B significantly inhibits melanoma formation in the BRAF/phosphatase and tensin homolog (PTEN) mouse melanoma model." (PMID 36091786, 2022).